INS (insulin)
Diseases named in the same sentence as INS in open-access papers (continued):
Sharing a sentence is not in itself a finding about the gene and the disease.
Insulin resistance (continued). "Insulin resistance, characterized by elevated basal and stimulated levels of insulin, is inextricably associated with older age." (PMID 27095270, 2016). "Puberty is associated with a physiological state of insulin resistance, and conditions as premature pubarche have also been related to reduced insulin sensitivity and shown to be more frequent in subjects born SGA." (PMID 27746590, 2016). "Elevated plasma levels of free fatty acids (FFAs) are known to cause peripheral (muscle) insulin resistance by inhibiting insulin-stimulated glucose uptake and glycogen synthesis." (PMID 27478435, 2016). "As steatosis is often associated with insulin resistance, we investigated glucose metabolism and insulin signaling in the liver of ACE2−/y mice." (PMID 28101297, 2016). "Recently, a study involving more than 4000 participants in Korea revealed that insulin level and insulin resistance were inversely associated with dietary intake of flavonols and flavones, thereby reducing the risk of T2DM." (PMID 26308010, 2015). "The aim of this study was to investigate the regulating effect of pericentrin (PCNT) on insulin secretion in the development of insulin resistance and to determine the underlying mechanism." (PMID 26083368, 2015). "These factors act in concert to cause adipocyte dysfunction and insulin resistance directly by decreasing insulin signaling, or indirectly by inducing inflammatory gene expression and interfering with PPARγ activity." (PMID 26030149, 2015). "Although autonomic dysfunction predicts events in Caucasians, it remains to be determined if a lower HRV is associated with post-load plasma blood glucose, insulin concentrations, and insulin resistance and sensitivity." (PMID 26277879, 2015). "Insulin resistance is associated with compensatory hyperinsulinemia, and insulin has direct functions in the heart other than regulating glucose uptake." (PMID 25973404, 2015). "Despite the well-documented association between insulin resistance and cardiovascular disease, the key targets of insulin relevant to the development of cardiovascular disease are not known." (PMID 25849138, 2015). "In this study we observed that an ‘energy dense, high fat and low fibre’ DP is prospectively associated with unfavourable cardiometabolic risk factors, including higher levels of insulin and insulin resistance, in boys and girls." (PMID 26026208, 2015). "Obesity is a risk factor for type 2 diabetes and insulin resistance and therefore can affect Mg status by altering glucose metabolism and insulin action." (PMID 25947295, 2015). "The polymorphism occurs naturally in the human population and is associated with variation among individuals in insulin secretion, and insulin resistance." (PMID 25774510, 2015). "In contrast, hyperinsulinemia and insulin resistance, which are associated with an impaired vasodilatory effect of insulin, have been demonstrated to be an independent risk factor for coronary artery disease." (PMID 26124827, 2015). "Large adipocytes are less sensitive to insulin than smaller adipocytes and adipocyte size is positively associated with insulin resistance and Type 2 diabetes in both humans and rodents." (PMID 26098756, 2015). "Decreased parasympathetic and increased sympathetic activities were associated strongly with changes in insulin sensitivity compared with indices of insulin resistance or glucose abnormalities in our study." (PMID 26277879, 2015). "Peripheral insulin resistance occurs because of impaired insulin-induced signal transduction that normally causes membrane translocation of glucose transporters such as GLUT4 from the cytosol." (PMID 26543713, 2015). "A number of cross-sectional studies in children and adults, as well as prospective studies in adults, have reported associations of glucose, insulin and insulin resistance with CVD risk factors." (PMID 25940643, 2015).
Insulin resistance (continued). "A growing literature suggests that the insulin resistance and dysregulation of insulin signaling associated with T2D are precursors to both cognitive impairment and AD." (PMID 26217222, 2015). "HbA1c and specially insulin levels were associated with metabolic syndrome criteria, their clustering, and insulin resistance." (PMID 26241903, 2015). "In line with previous reports, HFD-induced insulin resistance was also associated with impaired insulin signaling in the brain." (PMID 26658276, 2015). "Our observations corroborate previous studies showing younger menarcheal age to be associated with higher fasting insulin concentrations and increased insulin resistance as measured by HOMA-IR." (PMID 26061526, 2015). "GADD34 -deficient mice become insulin resistance by aging, which is caused by the decrease of insulin-Akt signaling." (PMID 26316333, 2015). "Hypothyroidism has been associated with glucose and insulin metabolism disorders that affect insulin secretion in response to glucose, hyperinsulinemia, altered peripheral glucose disposal, and insulin resistance." (PMID 26870107, 2015). "Insulin resistance also is a major risk factor for developing type 2 diabetes caused by the inability of insulin-target tissues to respond properly to insulin." (PMID 25713812, 2015). "Among participants with metabolic syndrome (N = 735), high HbA1c was mainly associated with high glucose and insulin resistance while high insulin was additionally associated with high waist circumference." (PMID 26241903, 2015). "Insulin resistance and increased insulin levels are associated with increased risk and mortality in women with cancer, particularly breast, endometrial, and ovarian cancers." (PMID 25866823, 2015). "The hyperglycaemia is attributed to a combination of impaired insulin utilization (insulin resistance) and a limited ability to compensate with insulin production (net insulin deficiency)." (PMID 25881031, 2015). "In boys, the levels of uPA were not significantly related to age, components of MetS, hsCRP, insulin resistance, or insulin secretion, but suPAR levels were associated with hsCRP." (PMID 26633970, 2015). "We examined the association of HbA1c and fasting insulin with clustering of metabolic syndrome criteria and insulin resistance as two essential characteristics of the metabolic syndrome." (PMID 26241903, 2015). "Perturbations in downstream proteins involved in insulin signaling pathways have been found in insulin resistance and inflammation-associated T2DM." (PMID 25623542, 2015). "These markers have been shown to be associated with indirect measurements of insulin resistance, including fasting insulin levels and HOMA-IR, and were also shown to be in conjunction with insulin sensitivity measured by the gold-standard clamp method." (PMID 25986611, 2015). "Overexpression of miR-29a/b/c causes insulin resistance, similar to that of incubation with high glucose and insulin." (PMID 25333294, 2015). "Anthropometric indices correlated with insulin and insulin resistance, but their associations with other cardiometabolic risk factors was almost inexistent." (PMID 26546280, 2015). "Vitamin D deficiency also has been shown to increase insulin resistance and reduce insulin secretion, which has shown to be a risk factor for gestational diabetes." (PMID 25898021, 2015). "A broad comparison from a different cohort of varied HD duration with mixed levels of insulin will also clarify the effects of ΔSI, revealing further details in the underlying contributors of specific insulin resistance." (PMID 25750607, 2015). "But higher dexamethasone dose intake is also associated with increased insulin-resistance and this can result in higher glucose and insulin levels." (PMID 26015297, 2015). "Improvement was linked to preoperatively elevated insulin resistance, which normalized after resection and was accompanied by a decrease in fasting- and glucose-stimulated insulin secretion." (PMID 26248027, 2015).
Insulin resistance (continued). "Is insulin resistance due to a graded loss of insulin response at the individual cellular level or does it reflect changes in the fraction of cells responding to insulin?" (PMID 25768970, 2015). "Both excess LH stimulation and elevated insulin levels, due to decreased receptor levels and resulting insulin resistance, can cause increased androgen production from the ovary." (PMID 26305227, 2015). "Decreased insulin secretion due to the loss of β-cell mass or impaired β-cell function and increased insulin resistance are considered two major factors leading to impaired glucose tolerance in the elderly." (PMID 26107521, 2015). "HET reduced weight gain, fasting blood glucose and plasma insulin levels as well as homeostasis model assessment of insulin resistance (HOMA-IR) and alleviated obesity and T2DM associated oxidative stress and hypertension in rats." (PMID 26003803, 2015). "Increased reactive oxygen species (ROS) level also causes insulin resistance in peripheral tissues while deteriorating insulin secretion from islet cells." (PMID 26494989, 2015). "Multiple studies have indicated that Akt2 is the primary isoform responsible for insulin-stimulated glucose uptake in humans as well as rodents and dysfunctional Akt2 is associated with insulin resistance and impaired glucose tolerance." (PMID 26465754, 2015). "An association between insulin resistance and amylin is supported by studies showing elevated levels of this hormone in patients with impaired glucose regulation and in insulin resistant elderly women." (PMID 25807378, 2015). "T2D is a metabolic disorder characterized by chronic hyperglycemia and associated with insulin resistance and/or impaired insulin secretion." (PMID 26366137, 2015). "T2D is a chronic metabolic disease, characterized by high levels of glucose in the blood, and frequently caused by a deficiency of insulin secretion and/or the development of insulin resistance (the inability of cells to respond to the insulin)." (PMID 25852736, 2015). "Although there is a general consensus that insulin resistance is caused by defects in insulin signaling, many causes have been proposed to explain how these insulin signaling defects appear in NAFLD." (PMID 25875942, 2015). "The insulin level and the insulin resistance both represent the main cause of inducing the hyperglycemia by destroying the structure of the pancreas and the β-cell function." (PMID 26132991, 2015). "Excessive insulin action associated with insulin resistance is thought to progress these multiple cancer phenotypes." (PMID 26690494, 2015). "We herein demonstrated for the first time the beneficial effects of L-Cit on improved insulin resistance associated with enhanced insulin sensitivity." (PMID 26084330, 2015). "Chronic inflammation is associated with obesity-induced insulin resistance, largely by inhibiting the insulin pathway at IRS-1." (PMID 26023930, 2015). "The underlying mechanism for this association is that the NAFLD is strongly associated with both hepatic and adipose tissue insulin resistance as well as reduced whole-body insulin sensitivity." (PMID 26569494, 2015). "In correspondence with this, higher DAG level in muscle has been associated with obesity and insulin resistance in both rats and humans, while muscle ceramides are also elevated in lean or obese insulin resistant humans and rats." (PMID 25790476, 2015). "Unlike orthosteric IR activators, ligands that bind allosterically to IR and sensitize insulin action would represent a significant therapeutic advancement with the potential of alleviating insulin resistance and minimizing hypoglycemia risk." (PMID 25799496, 2015). "Peripheral insulin resistance is often associated with impaired insulin signaling and dysregulated glucose metabolism in the brain." (PMID 26658276, 2015).
Insulin resistance (continued). "In rodent lipid infusion studies, insulin resistance develops, and increased concentrations of long-chain acyl CoAs have been associated with insulin resistant skeletal muscle." (PMID 25685986, 2015). "Higher levels of circulating insulin associated with insulin resistance have shown a proliferative effect on thyroid tissue resulting in larger thyroid size with increased formation of nodules." (PMID 26435714, 2015). "Serum leptin seems to have an association with NAFLD both in male and female prediabetic subjects and this association in turn, is mediated by insulin secretory dysfunction and insulin resistance among these subjects." (PMID 26569494, 2015). "Insulin resistance is associated with reduced inhibition of hormone-sensitive lipase in adipose tissue by insulin, leading to increased lipolysis and, thereby, augmented NEFA portal flux to the liver." (PMID 25725623, 2015). "Impaired insulin signaling leads to reduced glucose uptake and glycogen synthesis, eventually causing insulin resistance in hepatocytes." (PMID 25884658, 2015). "The mechanisms underlying type 2 diabetes include insulin secretion by pancreatic β-cells and insulin resistance, which involves hepatocytes, adipocytes and myocytes." (PMID 25859278, 2015). "The current study confirms that GDM is associated with increased insulin resistance and β-cell dysfunction, as well as reduced insulin sensitivity and secretion." (PMID 25915047, 2015). "Insulin resistance and elevated C-peptide, a marker of insulin release, confer a higher risk of endometrial cancer." (PMID 26134033, 2015). "Insulin resistance, the hallmark of type 2 diabetes, is caused by a defect of insulin action resulting in dysfunctional glucose uptake into insulin-sensitive tissues (i.e., striated muscle and adipose tissue) such as the heart." (PMID 26539824, 2015). "The rs1044498, SNP variation causes a gain‐of‐function mutation that causes overexpression in peripheral insulin target tissues and is associated with human insulin resistance." (PMID 26740948, 2015). "Taken together, these data indicate that FMO3 expression, which is directly inhibited by insulin and induced by glucagon and corticosteroids, is increased in male mice with insulin deficiency/insulin resistance." (PMID 25849138, 2015). "Previous studies have also shown that PA can cause insulin resistance in insulin-target tissues, both in vitro and in vivo." (PMID 26193288, 2015). "Insulin is also a factor because maternal low protein diets increase the risk of insulin resistance in male offspring at 20 weeks of age." (PMID 26561832, 2015). "Our data underscore the complementary benefit of combining CGA to CrIII in terms of body weight loss and preserving insulin response during sustained high-fat intake, which commonly causes insulin resistance and visceral obesity." (PMID 26045713, 2015). "These two patterns are consistent with the transcriptomic changes associated to insulin resistance and insulin sensitivity, respectively, in human adipocytes." (PMID 25799240, 2015). "The ensuing insulin resistance causes disruption in the propagation of insulin signals on insulin-responsive cells." (PMID 26273674, 2015). "Many studies have shown that insulin resistance (IR) is directly associated with lipid disorders, which induced alterations of insulin action and signalling pathways." (PMID 26288372, 2015). "The physiological effects of HFD exposure and associated obesity, such as increased fasting insulin and insulin resistance, are well described in both rodents and humans." (PMID 26448649, 2015). "As early as 30 years ago, Vague and his colleague found that PAI-1 was linked to insulin resistance, insulin, and weight in obesity." (PMID 26633970, 2015). "Daily injection of 1 mg kg–1 FF for 7 days caused hyper-insulin resistance in an insulin-tolerance test." (PMID 27066265, 2015).
Insulin resistance (continued). "Similar to the findings in humans, there was a robust association between hepatic steatosis and plasma insulin (r = 0.47, p = 4.51 × 10−21), glucose (r = 0.23, p = 1.26 × 10−5) as well as insulin resistance (HOMA-IR) (r = 0.45, p = 2.18 × 10−20)." (PMID 26067236, 2015). "Carriers of T2D risk allele of rs4731702 manifested higher fasting insulin, which suggested a role of its residue gene region in insulin resistance." (PMID 26599349, 2015). "The hyperphosphorylation is associated with brain insulin resistance that results from the impairment of several pathways such as insulin and IGF-1 signaling." (PMID 25755673, 2015). "Evaluation of NHANES data (1999–2002) of adolescents aged 12–19 years demonstrated that higher levels of cardiorespiratory fitness were associated with better insulin sensitivity (i.e., less insulin resistance), especially in male students." (PMID 26378914, 2015). "Activation of proopiomelanocortin neurons by leptin has been shown to enhance insulin secretion and degree of insulin resistance and β-cell function are associated with leptin in patients with Type 2 diabetes." (PMID 25723719, 2015). "Excess FFA release not only causes peripheral insulin resistance, but also increases insulin secretion and impairs beta cell function." (PMID 26580649, 2015). "Insulin was associated with the criteria more strongly than HbA1c and similarly to Homeostatic model assessment - Insulin Resistance (HOMA-IR)." (PMID 26241903, 2015). "Some studies have indicated that elevated insulin concentrations and insulin resistance are associated with an increased risk of Alzheimer’s disease and impairments in cognitive function." (PMID 25798199, 2015). "Decreased insulin sensitivity, due to insulin resistance, has been associated with increases in the serum levels of platelet factors, such as fibrinogen and von Willebrand factor, and thus increased potential for hypercoagulability which is a CHD hallmark." (PMID 25774201, 2015). "HFD was associated with insulin resistance, and elevated serum levels of insulin and IGF-1 were supposed to exert promotion of PCa development and progression." (PMID 25722971, 2015). "The possibility remains that monocyte/macrophage-secreted MVs can inhibit insulin signaling in adipocytes, thereby causing the insulin resistance observed in obese adipose tissue." (PMID 26064180, 2015). "This has been confirmed by in vitro studies in animal models suggesting its role in improving insulin sensitivity and secretion, though the associations between 25OHD, glucose homeostasis, and insulin resistance in humans seems to be inconsistent." (PMID 25887335, 2015). "Young GADD34 -deficient mice are higher level of insulin signaling, which changed to insulin resistance by aging." (PMID 26316333, 2015). "In contrast to T2DM, which is a relative insulin deficient state with the pathology attributed largely to insulin resistance, it is a defect in insulin secretion that is the principal pathology of both HNF1A-MODY mutation carriers and T1DM." (PMID 26110317, 2015). "Transcript expression in human tissues is correlated with insulin sensitivity and linked to dysregulation of genes involved in the pathophysiology of obesity, insulin resistance, and T2D." (PMID 25868721, 2015). "Tipping the balance in favour of ceramide accumulation has been shown to cause insulin resistance whereas SphK1 prevents ceramide accumulation by promoting its metabolism to S1P and augmenting insulin action." (PMID 25866760, 2015). "Nitric oxide seems to play an important role in the development of insulin resistance, and its deficiency is believed to reduce blood flow to insulin-sensitive tissues,i.e." (PMID 26380228, 2015). "Activation of NF-κB is a common characteristic of many tumors and has been associated with insulin resistance and elevated circulating levels of insulin and/or IGF-I." (PMID 26029167, 2015).